OAS1 (2'-5'-oligoadenylate synthetase 1)
Diseases named in the same sentence as OAS1 in open-access papers (continued):
Sharing a sentence is not in itself a finding about the gene and the disease.
COVID-19 (continued). "Genetically regulated loss of OAS1 expression contributes to impaired spontaneous clearance of SARS-CoV-2 and an increased risk of hospitalization for COVID-19." (PMID 38162574, 2023). "In 2022, several studies found that OAS1 was an effector gene affecting the severity of COVID-19 in Europe and Africa." (PMID 37746262, 2023). "Single nucleotide variant rs10735079 (A > G) is responsible for gene clusters OAS1, OAS2 and OAS3, and is among the COVID-19 genes." (PMID 37896870, 2023). "An upregulation of OAS1 and MxA despite little induction of the interferon response was also observed in COVID-19 patients, and similar results were reported on a three-dimensional human alveolar stem cell model." (PMID 37834031, 2023). "The study revealed that ACE2 rs2074192 (allele T), IFNAR2 rs2236757 (allele A), OAS1 rs10774671 (allele A), CD40 rs4813003 (allele C), CASP3 rs113420705 (allele C) and male sex contribute to severe COVID-19 course and MIS-C in 85.6% of cases." (PMID 37896870, 2023). "Variations in the alternative splicing forms of OAS1 have been reported as indicators of COVID-19 severity, with similar findings noted in other viral infections." (PMID 37928544, 2023). "The multifactorial analysis shows that, in addition to ACE2, IFNAR2, OAS1, and CD40 genes, the CASP3 rs113420705 gene (allele C) makes the clinical outcome of COVID-19 in males worse." (PMID 37896870, 2023). "Regression analysis showed that COVID-19 susceptibility in children increases in cases of interactions of IFNAR2 rs2236757, OAS1 rs10774671, OAS3 rs10735079, CD40 rs4813003 and CASP3 rs113420705." (PMID 37896870, 2023). "This approach discovered 1,275 eQTL loci, of which 988 were colocalized with one or more GWAS loci of autoimmune and infectious diseases, including COVID-19 at the OAS1 locus." (PMID 37308670, 2023). "Using human genetics methods, several host factors have been identified to influence COVID-19 severity, including OAS1, type I interferon and chemokine genes." (PMID 37794074, 2023). "Only the OAS1 ISG isoform appears functionally critical for anti-SARS-CoV-2 activity, and the early control of SARS-CoV-2 replication through OAS1 appears to be an important determinant of COVID-19 disease severity." (PMID 37364688, 2023). "While fibroblasts are not the primary cellular target of SARS-CoV-2 infection (which mostly targets epithelial cells), we detected a colocalization between OAS1 eQTL and COVID-19 GWAS locus, which we then also found in PBMCs from patients with COVID-19." (PMID 37308670, 2023). "Reduced OAS1 expression due to a common haplotype is proven to be related to the severity of COVID-19." (PMID 38162574, 2023). "The OAS1 effect on COVID-19 in Europeans has been well-replicated in previous GWAS and MR studies, with our findings also validating the effects of OAS1 on COVID-19 severity via alternative splicing." (PMID 35772218, 2022). "We conclude that decreased OAS1 expression due to a common haplotype contributes to COVID-19 severity." (PMID 35835913, 2022). "Using our eQTL resource in conjunction with COVID-19 GWAS, we conducted MR analyses that identified seven genes, including OAS1 and IFNAR2, as putatively causal for COVID-19 severity." (PMID 36424512, 2022). "Using CASA, we also found the exon 7 of the OAS1 gene shows a different inclusion level at chr12:112919388 between healthy and COVID-19, the reference SNP cluster ID rs10774671 was included in alternative splicing event." (PMID 36266726, 2022). "Five essential genes (IFNAR2, TYK2, OAS1, DPP9, and CCR2) have been linked to the most severe forms of COVID-19 disease, suggesting possible drug targets and vaccine epitopes." (PMID 35454970, 2022). "The OAS1, SERPINA1 and ICAM1 effects were replicated using updated COVID-19 severity data in the two ancestries respectively, where alternative splicing events in OAS1 and ICAM1 also showed marginal effects on COVID-19 severity in Europeans." (PMID 35772218, 2022).
COVID-19 (continued). "Furthermore, COVID-19-related changes in ncRNAs and transcription factors reflect increased risks of developing lung inflammation and cholinergic neurons demise, and elevated risk of severe COVID-19 was linked to the genetic OAS1 variant that associates with elevated risk of AD." (PMID 35211331, 2022). "MR and colocalization prioritized four protein targets, FCRL3, ICAM5, ENTPD5 and OAS1 that showed effect on COVID-19 severity in European ancestry." (PMID 35772218, 2022). "Of multiple associated genetic variants, we identified rs10774671 and rs1131454 as the most functional within OAS1 for COVID-19 severity and SARS-CoV-2 clearance." (PMID 35835913, 2022). "The coloc-first approach revealed a common genetic signal between OAS1 and COVID-19 in two out of seven COVID-19 phenotypes (PP.H4 = 0.88 in COVID-19 vs. population, and 0.82 in hospitalised COVID-19 vs. population)." (PMID 34402426, 2021). "(G) OAS1 rs10774671 genotype frequency in severe COVID-19 cohort and matched healthy control subjects." (PMID 34342578, 2021). "Our human genetic data further supports the contribution of OAS1 rs10774671 to severity of COVID-19." (PMID 34342578, 2021). "Prenylated OAS1 has contributed to the prevention of severe COVID-19 in a substantial fraction of infected individuals (likely measured in “hundreds of thousands” in the UK alone)." (PMID 34581622, 2021). "Of particular interest in the context of the COVID-19, a recent report describes that the interferon-induced, dsRNA-actived antiviral enzyme OAS1 significantly contributes to the antiviral response against SARS-CoV-2." (PMID 34887937, 2021). "We suggest that genetically-regulated loss of OAS1 expression contributes to impaired spontaneous clearance of SARS-CoV-2 and elevated risk of hospitalization for COVID-19." (PMID 34282422, 2021). "Out of 22 eligible articles that investigated candidate genes (2 as associated with COVID-19), the top-ranked genes in the number of studies were ACE2, CLEC4M (L-SIGN), MBL, MxA (n = 3), ACE, CD209, FCER2, OAS-1, TLR4, TNF-α (n = 2)." (PMID 32917282, 2020). "In addition, the functional variants OAS1 rs4767027C>T, OAS1 rs1131454A>G, and OAS3 rs10735079A>G have also been associated with susceptibility to and/or severity of COVID-19." (PMID 41977153, 2026). "There is mounting evidence suggesting that OAS1 may be an effector gene influencing COVID-19 severity." (PMID 40002189, 2025). "OAS1 was selected based on its relevance in COVID-19 literature and its metabolomic signatures." (PMID 40240424, 2025). "However, while comparing LTBi positive individuals between HC and COVID-19, we found higher OAS-1 mRNA levels in the LTBi COVID-19 as compared to LTBi HC group." (PMID 41468475, 2025). "Moreover, in people with severe COVID-19 the infection reveals a diminished antiviral response marked by the downregulation of antiviral genes such as OAS1, SAMD9L and IFIT2, and suppression of antiviral immune response pathways." (PMID 41168347, 2025). "This study investigated the potential influence of SNPs in genes associated with the interferon pathway (IFNAR2 rs2236757), antiviral response (OAS1 rs10774671, OAS3 rs10735079), and viral entry (ACE2 rs2074192) on COVID-19 severity and their association with MAFLD." (PMID 39296547, 2024). "In addition to COVID-19, OAS1 variations and autoinflammatory immunodeficiency were recently correlated in two other reports." (PMID 38343534, 2024). "No allele or genotype of the OAS1 or DPP9 loci was significantly associated with the severe COVID-19 phenotype." (PMID 38694517, 2024). "This suggests that variations in these genes, such as OAS1 and OAS3, might influence our susceptibility to severe COVID-19." (PMID 39296547, 2024). "Therefore, based on the model, the key components of COVID-19 susceptibility in childhood are alleles of genes IFNAR2 rs2236757, OAS1 rs10774671, OAS3 rs10735079, CD40 rs4813003 and CASP3 rs113420705." (PMID 37896870, 2023).
COVID-19 (continued). "Moreover, other regions of genetic susceptibility for COVID-19 severity have been described, such as those related to the ABO blood group system or the antiviral response (OAS1, OAS2, OAS3, TYK2, IFNAR2 or IL-10)." (PMID 37809329, 2023). "Interestingly, this same genetic locus of OAS1 has also been found to have a connection with SARS-CoV-2, the virus causing COVID-19." (PMID 38259635, 2023). "In addition, we confirmed that the OAS1 gene is also a strong eQTL in PBMCs and colocalizes well with the COVID-19 GWAS locus with the posterior probability of 0.99." (PMID 37308670, 2023). "Studies show that the presence of the risk allele G rs10735079 gene leads to reductions in the OAS1 level, which proves the existence of a negative inverse relationship between the severity of the course of COVID-19 and the level of OAS1." (PMID 37896870, 2023). "It has been noted that the gene OAS1 is an important gene influencing COVID-19 patients." (PMID 36913345, 2023). "While the OAS1 Neanderthal mutation has been linked to a milder COVID-19 pathology, we did not identify significant immune transcriptomes differences in the 25 patients homozygous for this mutation." (PMID 35181735, 2022). "Protein level of OAS1 showed an effect on COVID-19 severity in Europeans using both HGI v6 (OR=0.827, 95%CI=0.732 to 0.934, P = 2.3 × 10−3) and GenOMICC v2 data (OR=0.735, 95%CI=0.627 to 0.863, P = 1.7 × 10−4), where no valid OAS instrument was available in Africans." (PMID 35772218, 2022). "In addition, our study identified four additional protein targets, FCRL3, ICAM5, ENTPD5 and OAS1, that showed effect on COVID-19 severity in Europeans." (PMID 35772218, 2022). "In the case of OAS pathways, such mechanistic understanding is crucial, as introgressed variants linked to the expression of OAS1-2-3, including one emVar identified in the MPRA, have been found to be somewhat protective against severe COVID-19 response (Zeberg and Pääbo 2020b)." (PMID 34662402, 2022). "Thus, genetically regulated OAS1 expression contributes to association with SARS-CoV-2 clearance and risk of hospitalization for COVID-19." (PMID 35835913, 2022). "For OAS1, we observed little evidence of a causal effect of gene expression level on COVID-19 severity (P = 0.568)." (PMID 35772218, 2022). "In Europeans, the risk of hospitalized vs. non-hospitalized COVID-19 was associated with a single 19Kb-haplotype comprised of 76 OAS1 variants included in a 95% credible set within a large genomic fragment introgressed from Neandertals." (PMID 34282422, 2021). "Finally, our human genetic analysis shows that the OAS1 splice-site SNP responsible for production of the OAS1 p46 isoform correlates with protection from severe COVID-19." (PMID 34342578, 2021). "Therefore, the aim of this study was to determine whether four variants in the OAS1 and OAS3 genes are associated with susceptibility to COVID-19 and with the clinical signs and symptoms of the disease." (PMID 41977153, 2026). "However, in the context of our study, IFN-α levels were significantly lower in carriers of the A allele of OAS1 rs10774671, which could be explained by the generally low levels of IFN-α in children with COVID-19." (PMID 40066463, 2025). "Additionally, specific OAS1 variants – such as rs10735079, rs6489867, and rs4767027 – have been implicated in susceptibility to SARS-CoV-2 infection, further underscoring the complex relationship between genetic factors and COVID-19 outcomes." (PMID 40543387, 2025). "Therefore, the objective of our study is to investigate genetic variants in the genes AQP3, ARHGAP27, ELF5, IFNAR2, LIMD1, OAS1 and UPK1A, which were selected due to the association of these genes with the severity of COVID-19, in a sample of Amazonian indigenous peoples." (PMID 38543725, 2024). "Therefore, the lack of association of OAS1 rs10774671 and COVID-19 susceptibility, severity and/or outcome should be considered with caution." (PMID 38673053, 2024).
COVID-19 (continued). "Allele T ACE2 rs2074192 (OR = 3.45; p = 0.009), allele A IFNAR2 rs2236757 (OR = 2.62; p = 0.039), allele A OAS1 rs10774671 (OR = 4.60; p = 0.003) and allele C CD40 rs4813003 (OR = 4.75; p = 0.037) are associated with severe COVID-19 that could advance to MIS-C." (PMID 37896870, 2023). "Furthermore, the OAS1 gene served as the genetic link between AD and COVID-19." (PMID 38259635, 2023). "Therefore, this evidence suggested that the induction of genes such as OAS1 in severe COVID-19 conditions could have a better prognosis in those patients." (PMID 36553678, 2022). "The genetically-predicted protein levels of OAS1 (OR=0.440, 95%CI=0.315 to 0.615, P = 1.57 × 10−6), FCRL3 (OR=1.032, 95%CI=1.030 to 1.034, P = 2.40 × 10−191) and ICAM5 (OR=0.780, 95%CI=0.691 to 0.880, P = 5.74 × 10−6) showed MR association with COVID-19 severity using data from GENOMICC." (PMID 35772218, 2022). "Interestingly, OAS1 (2’-5’-Oligoadenylate Synthetase 1) shows higher expression in patients with mild symptoms, which agrees with the recent findings that higher plasma OAS1 concentrations are associated with reduced COVID-19 severity." (PMID 35634344, 2022). "Hence, the in-silico validation of our hub genes in those expression datasets pointed out that ISG15 and MX1 are the most conserved up-regulated genes across COVID-19 datasets of immunological cells, while OAS1 and MX1 are those with lower gene expression levels in tissue-specific healthy samples." (PMID 36553678, 2022). "However, among the IFN-I related 14 genes, OAS1 may play a complementary role in the differential diagnosis of COVID-19 and Influenza A/B/RSV." (PMID 34880855, 2021). "Since the OAS1 rs10774671 A/G variant generates the OAS1 p42 and p46 isoforms, respectively, that affected SARS-CoV-2 titers in vitro, we tested whether this SNP is associated with COVID-19 disease severity." (PMID 34342578, 2021). "However, the SNPs representing the common genetic signal between OAS1 and COVID-19 phenotypes (12:112919637:G:A and 12:112919388:G:A) were missense variants in OAS1 gene or in LD with missense variants at r2 >0.8, rendering their effect estimates potentially biased due to aptamer binding effects." (PMID 34402426, 2021). "Although the OAS1 promoter did not directly overlap COVID-19-risk variants, we found several fine-mapped COVID-19-risk variants, associated with OAS1 expression (eQTLs), directly overlapped an intergenic transposase-accessible and H3K27ac-enriched peak region, located 20 kb away from OAS1 promoter." (PMID 34799557, 2021). "Thus, the correct targeting of OAS1 and the subsequent inhibition of SARS-CoV-2 likely underpins the genetic association of alleles containing a G at Rs10774671 with reduced susceptibility to infection and severe disease in COVID-19." (PMID 34581622, 2021). "OAS1, OAS2, and OAS3 were overexpressed in hospitalized patients with severe COVID-19 compared with healthy subjects (HS) (log2 fold change [95% CI]: OAS2: 4.312 [4.161-4.602], OAS3: 1.660 [1.485-1.916]; p = 0.0040 for both)." (PMID 41899113, 2026). "As an exemplar case study of the application of our metabolomic signatures, here, we discuss in detail the cellular biology of two well-known genes for COVID-19 severity namely LZTFL1 and OAS1." (PMID 40240424, 2025). "Correlation plots between TMPRSS2 and commonly upregulated genes were representively shown for OAS1, STAT1 and IRF7 from COVID-19 vs. healthy PBMNCs." (PMID 40055791, 2025). "Previously, we have published and demonstrated the specific roles of the ACE2 rs2074192, IFNAR2 rs2236757, OAS1 rs10774671, CD40 rs4813003, and CASP3 rs113420705 genes in predicting severe COVID-19 and multisystem inflammatory syndrome (MIS-C) in children." (PMID 40066463, 2025). "This study highlights the significant impact of genetic variations in IFNAR2, OAS1, OAS3, and ACE2 on the clinical and laboratory outcomes of COVID-19 patients receiving Paxlovid treatment." (PMID 40278335, 2025).
COVID-19 (continued). "The increased expression of OAS1, MAVS and SOCS3 mRNA in COVID-19 was consistent for both active and recovered cases." (PMID 41468475, 2025). "Based on relevant results reported in the existing literature and a previous study of our group, the genes CCL5, OAS1, IRF9, IFI6, TGFB1, IL1B, and TFRC were analyzed in the present study in relation to the severity of COVID-19." (PMID 38731851, 2024). "Previous work has identified common OAS1 haplotypes responsible for a decrease in protein abundance through the expression of NMD sensitive transcript p42, which contributes to COVID-19 severity." (PMID 39091463, 2024). "Specifically, in COVID-19, these genes were CD52, ISG15, and MMP9; in influenza, they included IFI44L, IFIT3, ISG15, and OAS1; and in HIV, OAS1 was identified." (PMID 38601162, 2024). "Using age-based stratification analysis in adjusted genetic models, the interaction of CCL2, OAS1, and DPP9 SNVs with the presence of the severe COVID-19 phenotype was examined." (PMID 38694517, 2024). "Another study developed in 34 Spanish hospitals with 11,939 positive cases of COVID-19 identified the relationship of the AQP3, ARHGAP27, ELF5, IFNAR2, LIMD1, OAS1 and UPK1A genes with the severity of the disease." (PMID 38543725, 2024). "Another study highlighted that a Neanderthal-derived haplotype encompassing the genes OAS1, OAS2, and OAS3 conferred protection against COVID-19, with OAS3 showing the most substantial correlations." (PMID 38673053, 2024). "This suggests that the inflammasome defect in COVID-19 PMNs is at the transcriptional level when using IFN-I as the priming factor, while high OAS1 gene expression indicates transcriptional defect is restricted to individual genes." (PMID 39172744, 2024). "In the present study, the differential expression of seven genes related to immunity, IRF9, CCL5, IFI6, TGFB1, IL1B, OAS1, and TFRC, was analyzed in individuals with COVID-19 diagnoses of different disease severities." (PMID 38731851, 2024). "The increased expression of selected IFN-I (OAS1, OAS2, and IFIT1) and inflammasome related genes (CASP1, CASP5, NLRC5 and NAIP) between COVID-19 and HC PMNs was confirmed by RT-qPCR." (PMID 39172744, 2024). "Among these proteins, OAS1 and IRF9 have been reported as potential biomarkers for COVID-19 prognosis." (PMID 38731851, 2024). "In this study, the highest differentially expressed genes in COVID-19 (+) tissue, including ISG15 itself, IFIT1, RSAD2, OAS1, MX1, OASL, and IFIT3, are all important for the ISG15 pathway’s progression and are part of the lung tissue’s antiviral response." (PMID 38932146, 2024). "Previous research has highlighted the up-regulation of genes such as IFI44L, IFFI44, RSAD2, OAS1, EPSTI1, and OSAL in COVID-19, contributing to immune regulation." (PMID 38601162, 2024). "OAS1 gene, an interferon stimulated gene (ISG), showed significant upregulation by IFN-I in COVID-19 PMNs as compared to HC PMNs, while the inflammasome related genes IL-1β, CASP1 and NLRC5 were more efficiently induced in HC PMNs than COVID-19 PMNs." (PMID 39172744, 2024). "Genotyping for gene variants at rs1024611 (A>G), rs10774671 (A>G), and rs10406145 (G>C) of CCL2, OAS1, and DPP9 genes was performed on 100 COVID-19 patients (43 with severe form and 57 asymptomatic-mild) using RFLP-PCR." (PMID 38694517, 2024). "Seven new genes (AQP3, ARHGAP27, ELF5, IFNAR2, LIMD1, OAS1 and UPK1A) were related to the severity of COVID-19 in populations of European origin." (PMID 38543725, 2024). "Crucial factors for the development of severe COVID-19 or MIS-C are sex (male gender), ACE2 rs2074192, IFNAR2 rs2236757, OAS1 rs10774671, CD40 rs4813003 and CASP3 rs113420705." (PMID 37896870, 2023). "Through COVID-19-relevant transcriptome and enrichment gene sets, seven druggable targets with COVID-19-relevant functions were identified, including CCR9, CXCR6, XCR1, IL10RB, OAS1, OAS2, and OAS3." (PMID 37886583, 2023).